KRAS (KRas proto-oncogene, GTPase)
Diseases named in the same sentence as KRAS in open-access papers (continued):
Sharing a sentence is not in itself a finding about the gene and the disease.
cancer (continued). "Finally, Trametinib (MEKi) and SCH772984 (ERKi) alone modestly decreased proliferation in MEFs expressing KRAS mutants and selected cancer cell lines with KRAS mutations." (PMID 35879364, 2022). "However, more recent investigations have shown that HRAS, NRAS and KRAS, when mutated, are each associated with a distinct group of cancer types." (PMID 35204676, 2022). "Mutations of G12 in KRAS have been involved in different cancers." (PMID 35586192, 2022). "A possible explanation is that KRAS G12C mutation is more common among smokers, with roughly 93% of patients being current or former smokers in the latter trial, leading to a greater degree of molecular and genomic heterogeneity in these cancers." (PMID 36284306, 2022). "While somatic mutations, such as KRAS mutations, cause a series of downstream secondary alterations in the transcriptome of cancer cells, evidence showing the role of lncRNAs in the pathophysiology of hematological malignancies has drastically increased in the last decade." (PMID 34489556, 2022). "Survival pathways, such as resistance to cell death, may represent a promising treatment approach in KRAS mutated cancers." (PMID 35091677, 2022). "Thus, we next characterized the susceptibility of a set of human cancer cells with either oncogenic KRAS mutations or a BRAFV600E mutation to MEK1/2 inactivation mediated by LF-W271A." (PMID 35899070, 2022). "In addition, likely as an adaptive mechanism to bypass p110α and maintain PI3K signaling output, PI3K pathway mutations were more commonly present in cancers with KRAS G12R mutations compared to other variants." (PMID 36124727, 2022). "Interestingly, the ratio of KRAS mutation types varies in different cancers and the KRAS G12D mutation type made up the highest proportion of tumors harboring a KRAS mutation." (PMID 35785187, 2022). "Furthermore, our KRAS-mutation signature was enriched in human KRAS-mutant cancers and predicted poor survival, a fact that further validates this gene set." (PMID 35327394, 2022). "Somatic mutations in 72 cancer-related genes were analyzed by next-generation sequencing, and KRAS mutations were classified into three categories: transversions (G > C or G > T; G12A, G12C, G12R, G12V), transitions (G > A; G12D, G12S, G13D), and wild-type (WT)." (PMID 36348317, 2022). "Recent analysis of human cancer genomes also showed that in addition to mutational processes, functional selection based on tissue-of-origin, signaling property of KRAS allele, as well as cooperating genetic events, also shape the mutational bias of KRAS gene across cancer types." (PMID 35482806, 2022). "Originally, macropinocytosis was reported in cancer cells bearing KRAS or PTEN mutations." (PMID 35287706, 2022). "In fact, KRAS mutations have been identified predominantly in lung (approximately 25% of cases), pancreatic (about 95% of case), and colorectal (approximately 35% of cases) cancers." (PMID 35449573, 2022). "However, Merck recently announced that it has abandoned its collaboration with Moderna to develop a cancer mRNA vaccine targeting KRAS mutation." (PMID 35517800, 2022). "The ASO strategy has also been proposed for the treatment of the KRAS mutation in cancer." (PMID 35890348, 2022). "Moreover, BI-3406 was found to prevent adaptative resistance to MEK inhibition in several KRAS-mutated cancer cell lines, and prevented ERK activation rebound following sotorasib treatment in vitro." (PMID 35251972, 2022). "In the adjusted analysis, multivariate Cox proportional hazards models confirmed significantly longer OS (HR = 0.55, P = .0008) and PFS with first-line systemic therapies (HR = 0.58, P = .0061) in patients with cancers harboring KRAS G12R vs. non-G12R mutations." (PMID 36124727, 2022).
cancer (continued). "However, despite this apparently clear picture from our in vitro work, we stress that this efficacy is not fully dependent on KRAS mutation status: our data from assays with diverse cancer cells bearing WT KRAS revealed a more complex interaction pattern." (PMID 35075146, 2022). "The enrichment of C6 analysis showed that the low expression of DIAPHs in PAAD of TCGA cohort was associated with genes downregulated by KRAS overexpression in cancer cell lines, whereas the high expression of DIAPH3 was associated with several oncogenes, such as E2F and EGFR." (PMID 36589226, 2022). "Recently, specific inhibitors (AMG510 and MRTX849) against G12C have offered an effective strategy to treat KRAS-driven cancers, suggesting that a range of mutant KRAS allele-specific targeted compounds could be druggable." (PMID 35563733, 2022). "Two‐hit inactivation of CDKN2A/2B was frequently found in KRAS‐mutant LUAD in The Cancer Genome Atlas (TCGA) database, and loss of CDKN2A/B fostered cellular proliferation, cancer cell differentiation, and metastatic behavior in genetically engineered mouse models of KRAS‐mutant lung tumorigenesis." (PMID 35253368, 2022). "In addition, cancer-associated mutations in iRhom2 act as sensitisers in this pathway by further increasing KRAS-induced shedding of ERBB ligands." (PMID 35971826, 2022). "A KRAS-associated cancer vaccine has emerged more than once." (PMID 36118526, 2022). "KRAS-G12D mutations are the one of most frequent oncogenic drivers in human cancers." (PMID 36430338, 2022). "KRAS G12 mutations are predominant (81%) in human cancers, followed by G13 (14%) and Q61 (2%)." (PMID 36080477, 2022). "Thus, SBT-100 has demonstrated binding to KRAS, subsequently, inhibiting of KRAS GTPase activity and suppression of downstream KRAS signaling by reducing pERK levels which resulted in the inhibition of the growth of cancer cells with activating KRAS mutations." (PMID 35886918, 2022). "Therefore it is necessary to elucidate influences of specific mutations on conformational dynamics of KRAS for discovering effective direct approaches to addressing RAS-driven cancers." (PMID 35586192, 2022). "However, a proper understanding of the mechanisms associated with KRAS activity in cancer will help in identifying proper therapeutic strategies." (PMID 36532636, 2022). "Approximately 15% of all cancer patients harbor mutated KRAS." (PMID 36065754, 2022). "Focusing on the KRASG12C mutant, this mutation is present in 12% of all KRAS-mutant cancers." (PMID 35045886, 2022). "KRAS mutations are frequent events in cancers and are shown to influence cancer cell metabolism." (PMID 35163079, 2022). "TBK1 is susceptible to hyperactivation in those cancer cells harboring KRAS-activating mutations." (PMID 35395857, 2022). "As for KRAS, it is a small GTPase (21 kDa) and 95% of PAAD patients had KRAS mutations, which caused KRAS to be constitutively activated resulting in uncontrolled cell proliferation and other processes that led to the development and spread of cancer." (PMID 35340619, 2022). "Besides, K-ras protein is found to be highly mutated in cancers with the bulk of the mutations occurring at position 12 which is termed KRAS G12D, with the change from glycine (G) to aspartic acid (D) or valine (V)." (PMID 35890342, 2022). "EGFR-mut cancers have fewer average mutations than KRAS-mut and NEK." (PMID 36612014, 2022). "Hence, most cancer patients with KRAS mutations exhibit resistance to various cancer therapies, leading to poor clinical outcomes." (PMID 35014625, 2022). "Fisher's exact test evaluated the association between cancer subtypes and KRAS variants." (PMID 35319967, 2022).
cancer (continued). "This included targets of drugs currently used to treat cancers where KRAS is frequently mutated." (PMID 36065754, 2022). "Oncogenic KRAS mutations lead to cancer chemoresistance targeting receptor target kinases (RTKs)." (PMID 35563733, 2022). "Interestingly, the mRNA levels of its downstream pathway mediators, such as MAPK1, JAK2 and KRAS, were found to be negatively associated with their methylation levels in most cancer types." (PMID 35978072, 2022). "Thus, the oncogenic KRAS gene, GFRs, mTORC1, and other factors are highly important for macropinocytosis-mediated cancer cell survival in nutrient-deficient environments." (PMID 36046825, 2022). "This highly significant finding establishes for the first time a direct effect of RAS on metabolism, represents the first demonstration of a biochemical difference between KRAS splice variants, and suggests a unique vulnerability for KRAS driven cancers that express oncogenic KRAS4A." (PMID 36393833, 2022). "The evidence provides certain clues for how KRAS-mutated cancer cells may succeed in a nutrient competition." (PMID 36151074, 2022). "However, previous studies mainly focus on oncogenic proteins themselves and are less associated with the KRAS surroundings, although cancer is closely related to oncoproteins and the surrounding environment." (PMID 36430338, 2022). "KRAS codon 12, 13, 61 and 146 specific point mutations occur frequently in KRAS-mutated cancers." (PMID 35456940, 2022). "Since the expression of WT or mutant KRAS has also been shown to be associated with resistance to these drugs in cancer, our study implicates that APE1-mediated KRAS expression may contribute to promoting resistance to these drugs in PDAC." (PMID 35286386, 2022). "Hyperactivation of KRAS signaling, which is usually caused by mutations of the KRAS gene, is commonly observed in cancer to drive uncontrolled cell proliferation and metastasis.The KRAS G12C mutation is one of the most extensively studied oncogenic driver mutations." (PMID 36104708, 2022). "Previous studies have shown that SMYD3 expression is increased in KRAS-mutated cancer, which may be due to the regulative effect of KRAS on SMYD3 gene transcription or protein stability." (PMID 34335697, 2021). "Indeed, genetic alterations in CDKN2A, CDK4, or CCND1 can be found in up to 20% of KRAS mutated NSCLC cancers." (PMID 33777798, 2021). "Similarly, in a cohort of cancer patients receiving everolimus, only 1/12 patients with KRAS mutation had disease control, while 15/31 wild cases benefited from the treatment." (PMID 34301278, 2021). "KRAS is upregulated in many cancers, and mutations in the KRAS gene can cause expression of aberrant KRAS proteins that promote the transformation of normal cells into cancerous cells by promoting cellular proliferation, survival, and cancer progression." (PMID 34680084, 2021). "Even though mutations in other RAS isoforms, including the neuroblastoma RAS viral (v-ras) oncogene homolog (NRAS) and Harvey rat sarcoma viral oncogene homolog (HRAS) are prevalent in many cancer types, mutations in KRAS account for 85% of all RAS isoform mutations." (PMID 33801965, 2021). "Although many cancers share similar metabolic adaptations, cancer cells rewire their metabolic programs in response to changes in the tumor microenvironment and oncogenic signals such as an activating KRAS mutation." (PMID 33806075, 2021). "In addition, the nuclear outlet receptor, exportin 1, has a strong synergetic lethal effect on KRAS-mutated cancer cells in vitro and in vivo." (PMID 34012925, 2021).
cancer (continued). "Notably, ARS-853 is a potent G12C allele-specific inhibitor that reduces cancer cell proliferation in vitro; its mechanism exploits the need of KRAS G12C nucleotide exchange to switch in the activated status, trapping it in the GDP-RAS state." (PMID 35004317, 2021). "KRAS mutations are one of the most prevalent oncogenic alterations in cancer." (PMID 35004309, 2021). "Also, a crosstalk between cancer-associated fibroblasts (CAFs) and KRAS mutant cancer cells has been shown." (PMID 33777798, 2021). "Altogether, it is apparent that AATs play a critical role in fulfilling the specific AA requirements in cancer cells, whereas the impact of oncogenic KRAS mutations on the expression and function of specific AATs in CRC cells are largely unknown." (PMID 34003553, 2021). "Thus, the notion of co-targeting MEK and CRAF or pan-RAF emerged; additionally, the combination strategy exhibited better anti-proliferation of cancer cells harboring KRAS mutations compared with MEK inhibitors alone." (PMID 34301278, 2021). "TBK1 is shown to be essential in some human cancer cell lines with KRAS mutations." (PMID 34108518, 2021). "Mutations in the KRAS oncogene have been associated with one third of all cancers." (PMID 33546207, 2021). "Moreover, there is a complex relationship of different molecular drivers, redundancy of signaling pathways, activation of bypass tracks, and the simultaneous involvement of immune-modulatory mechanisms in KRAS mutated cancer cells and the TME." (PMID 34064352, 2021). "We thus suggest that a PI4KA inhibitor may have a therapeutic window in situations whereby oncogenic KRAS signaling is already reduced, rendering cancer cells hypersensitive to any further loss of KRAS signaling." (PMID 34504076, 2021). "However, the abnormal activation alone HSF1 is not sufficient to cause cancer initiation, which means that the pro-tumorigenesis effect of HSF1 requires the contributions of other cancer-promoting mechanisms (such as the KRAS oncogene mutation)." (PMID 33422093, 2021). "Therefore, PBMC genetically engineered to express sp1- and sp2-specific TCRs were co-cultured with a series of cancer cell lines that harbored the G12V mutation within the KRAS gene." (PMID 33875134, 2021). "The KRAS oncogene is one of the most common mutation genes in cancer." (PMID 34692541, 2021). "Furthermore, the cancer cell lines differ in KRAS, BRAF and PIK3CA mutations, which are known to directly affect metabolic reprograming through their involvement in the MAPK/ERK signaling pathway." (PMID 33671096, 2021). "In addition, KRAS-mutated cancer cells have been shown to rely on serum lipids to maintain their proliferation and survival." (PMID 34947990, 2021). "In conclusion, we uncover a component of the KRAS interactome that induces a unique positive-feedback circuit promoting KRAS oncogenesis that could be leveraged for the treatment of KRAS mutation-positive cancers." (PMID 34504076, 2021). "The HRAS, NRAS, and KRAS genes are collectively mutated in a fifth of all human cancers." (PMID 34504076, 2021). "This implies that cancers driven by KRAS may be more susceptible to the PCAIs as the essential polyisoprenyl-driven functional interactions may be more easily uncoupled than would be the case for the other RAS proteins that are farnesylated and palmitoylated." (PMID 34830912, 2021). "KRAS- or BRAF-mutated cancer cells also exhibit oncogene addiction." (PMID 33793658, 2021).
cancer (continued). "Importantly, the activating alleles found in KRAS vary substantially across cancers, indicating possible differences in signaling behavior of the mutant proteins that exploit the environment of the specific cellular context." (PMID 33753749, 2021). "KRas’s higher susceptibility to chemical and UV mutagenesis may explain why it is more frequently seen in cancers, although more work is needed to understand why certain codons may be preferentially mutated in Ras isoforms." (PMID 34680208, 2021). "Finally, in KRAS-mutated cancer cells, oncogenic RAS allows the stabilisation of PD-L1 mRNA, leading to its increase and escape from immunosurveillance." (PMID 33257838, 2021). "Identification of KRAS mutational status is significant to manage these patients as the high-risk patients of PC may benefit from KRAS-driven therapeutic cancer vaccines." (PMID 35198564, 2021). "Interestingly, the adduction rate for KRAS codon 14 (K14) has been shown to be higher than codon 12 (K12) but has a much lower mutation rate in cancer." (PMID 34521464, 2021). "Finally, in the cancerous tissue subgroups alone, the miR-16 levels were significantly lower in KRAS-mutated vs. KRAS wild-type cancers (p = 0.0107)." (PMID 34948154, 2021). "In addition, low ERH expression is associated with better survival in cancer patients whose cancers harbor KRAS mutations while ERH was reportedly involved in cancer metastasis and EMT of bladder cancer." (PMID 33809701, 2021). "Further study is ongoing to enlarge this evidence on other KRas-mutated cancer cells with the final aim to evaluate whether NSC290956 can be a suitable therapeutic agent targeting metabolic vulnerability." (PMID 35069209, 2021). "We then considered the six different CRC molecular subtypes previously identified, C1 (immune pathways down regulated), C2 (enriched in dMMR tumors), C3 (KRAS mutated), C4 (enriched in cancer stem cells), C5 (wnt signaling up) and C6 (enriched for tumors with a normal-like gene expression profile)." (PMID 34503257, 2021). "Current knowledge has shed light on the importance of KRAS in cancer metabolism, which is mainly achieved when mutated KRAS enhances the transport of glucose intermediates into different pathways, such as the pentose phosphate pathway and the hexosamine biosynthesis pathway." (PMID 34571724, 2021). "KRAS is frequently associated with some of the deadliest forms of cancer." (PMID 33674596, 2021). "Finally, ferroptosis is a novel process related to cancer and, especially, to those harbouring KRAS mutations." (PMID 34359657, 2021). "However, there were studies that demonstrated that FTS alone promotes cell growth and induces the survival pathway in cancers carrying KRAS mutations." (PMID 33466836, 2021). "The MAPK pathway is commonly activated in cancers by driver mutations in KRAS, NRAS, and BRAF." (PMID 34214079, 2021).